ENSG00000238819
Synonyms: LOC124900371
Gene: Small nucleolar RNA gene on chromosome 15 (46,351,662 to 46,351,746, reverse strand). Ensembl gene ENSG00000238819.
Gene Ontology:
Biological process: RNA processing
Cellular component: nucleolus
Homologues: Orthologues: mouse Snord11 (74% identical), rat Snord11 (74% identical). Paralogues in human: SNORD11 (87% identical).